WNT11 (Wnt family member 11)
Diseases named in the same sentence as WNT11 in open-access papers (continued):
Sharing a sentence is not in itself a finding about the gene and the disease.
WNT11 also shares sentences with these, for which no sentence is quoted: cardiac hypertrophy (2 papers); triple-negative breast carcinoma (2); adenocarcinoma (1); Alzheimer disease (1); bladder carcinoma (1); bladder pain syndrome (1); brain tumors (1); breast adenocarcinoma (1); cervical cancer (1); colorectal adenocarcinoma (1); colorectal adenoma (1); Cyclopia (1); Cystic renal dysplasia (1); DiGeorge syndrome (1); Duchenne muscular dystrophy (1); endometrial cancer (1); esophageal cancer (1); glioblastoma (1); gout (1); hypertrophy (1); infarction (1); leukaemia (1); lymphoma (1); neurodegenerative disease (1); Onset (1); orofacial cleft (1); osteosarcoma (1); Pancreatic Ductal Adeno Carcinoma (1); Pleural effusion (1); psoriasis (1).
A further 9 diseases each share a sentence with WNT11 in 1 paper.